NKX2-5 (NK2 homeobox 5)
Diseases named in the same sentence as NKX2-5 in open-access papers (continued):
Sharing a sentence is not in itself a finding about the gene and the disease.
hypoplastic left heart syndrome (5 papers, 2021 to 2025). Hypoplastic left heart syndrome (HLHS) refers to the abnormal development of the left-sided cardiac structures, resulting in obstruction to blood flow from the left ventricular outflow tract. "NKX2-5, which has been associated with hypoplastic left heart syndrome, was upregulated in ACDMPV patients with deletion of FOXF1 and its enhancer." (PMID 34315444, 2021). "NKX2-5 is a pivotal TF in cardiac looping and its mutation brings about both hypoplastic right ventricle syndrome (HRVS) and hypoplastic left heart syndrome (HLHS) in humans." (PMID 35628576, 2022).
prostate carcinoma (5 papers, 2008 to 2024). A carcinoma that arises from epithelial cells of the prostate gland. "Among epigenetic biomarkers, most reports indicate GSTP1 hypermethylation as the diagnostic marker for prostate cancer; however, NKX2-5, CLSTN1, SPOCK2, SLC16A12, DPYS, and NSE1 also have been reported to be regulated by methylation mechanisms in prostate cancer." (PMID 24213111, 2011). "Compared to adjacent normal prostate, all 8 genes had significantly higher methylation in prostate cancer by t-test analysis (P<0.001 for NKX2-5; P<0.001 for SPOCK2; P = 0.004 for GALR2; P<0.001 for CLSTN1; P<0.001 for NSE1; P<0.001 for DPYS; P = 0.019 for FOXN4; P<0.001 for SLC16A12)." (PMID 18446232, 2008). "NKX2-5, RUNX1, TRPS1, FOXO1, and TP63 play a inhibitory roles in the development of prostate cancer." (PMID 38778150, 2024). "The transcriptional activities of NKX2-5, RUNX1, TRPS1, FOXO1, and TP63 are negatively correlated with LEGs, suggesting these suppress prostate cancer lineage plasticity through the RTK/RAS pathway." (PMID 38778150, 2024). "selected epigenetically altered genes in prostate cancer and found AR, GSTP1, RARB, SPARC, TIMP3, and NKX2-5 to be hypermethylated in AA patients." (PMID 36937425, 2023). "Based on methylation in primary tumors compared to normal adjacent tissues, NKX2-5, CLSTN1, SPOCK2, SLC16A12, DPYS and NSE1 are candidate biomarkers for prostate cancer (methylation range 50%–85%)." (PMID 18446232, 2008).
breast carcinoma (4 papers, 2006 to 2023). "Compared to adjacent normal breast, all 6 genes except NKX2-5 showed higher methylation in breast cancer by t-test analysis (P<0.001 for DPYS and EGFR5 P = 0.01 for SLC16A12; P = 0.002 for TOX; P = 0.003 for GALR2)." (PMID 18446232, 2008). "For example, NKX2-5 is methylated in prostate and colon cancer, but rarely in breast cancer." (PMID 18446232, 2008). "These genes included NKX2–5, which is predicted to regulate aberrant gene expression in human MDS and CLK2, a proposed oncogene in breast cancer; the promoters of both of these genes were hypomethylated in 15-month-old tet2m/m fish compared with 15-month-old tet2wt/wt fish." (PMID 37937078, 2023).
cardiac conduction disease (4 papers, 2019 to 2025). "The study contributes to the growing body of evidence on the role of NKX2-5 variants in cardiac conduction disorders." (PMID 40255339, 2025).
Ebstein anomaly (4 papers, 2012 to 2023). Ebstein's malformation is a rare congenital cardiac anomaly characterized by rotational displacement of the septal and inferior leaflets of the tricuspid valve such that they are hinged within the right ventricle, rather than as expected at the atrioventricular junction. "We then used this model to analyze organoid cells from an isogeneic line carrying an Ebstein’s anomaly associated genetic variant in NKX2-5, and we successfully recapitulated the disease’s atrialized ventricular defects." (PMID 35488063, 2022). "Notably, mutations in NKX2-5 have been found in some cases of Ebstein’s anomaly, a CHD that features a partially atrialized right ventricle." (PMID 33572830, 2021). "Furthermore, a single nucleotide variant in the NKX2-5 gene locus at the 673th nucleotide converting the 188th amino acid from Aspartate (N) to Lysine (K) was associated with Ebstein’s Anomaly, a congenital heart defect diagnosed with atrialized right ventricle and abnormal tricuspid valve." (PMID 35488063, 2022).
atherosclerosis (3 papers, 2016 to 2024). A disease characterized by the build-up of fatty material and calcium deposition in the arterial wall resulting in partial or complete occlusion of the arterial lumen. "Given that compromised endothelial function is a hallmark of early atherosclerosis, the effects of Nkx2‐5 on cell adhesion were further characterized." (PMID 27993833, 2016). "Furthermore, we demonstrated that the compromised endothelial function, which was considered as a hallmark of early atherosclerosis, could be improved by Nkx2‐5 gene transfer." (PMID 27993833, 2016). "Recently, a study using lentiviral induction of NKX2-5 in vivo suggested a protective role for transient endothelial NKX2-5 expression in atherosclerosis." (PMID 38652537, 2024). "Nkx2‐5 gene transfer markedly ameliorated atherosclerosis, with a diminished lesion area and a more‐stable plaque phenotype, and knockdown of Nkx2‐5 significantly exacerbated the disease." (PMID 27993833, 2016). "Molecular studies indicated that expression of specific members of matrix metalloproteinases and tissue inhibitor of metalloproteinases, which play a crucial role in the progression of atherosclerosis, were directly regulated by Nkx2‐5." (PMID 27993833, 2016). "Given that ApoE−/− mice demonstrate the atherosclerosis phenotype, we further performed immunostaining to analyze expression of Nkx2‐5 in diseased ApoE−/− mice and normal C57BL/6 mice." (PMID 27993833, 2016). "To characterize the involvement of Nkx2‐5 in atherosclerosis, we first examined expression of Nkx2‐5 in several human healthy vessels (saphenous vein and internal mammary artery) and carotid atherosclerotic plaques." (PMID 27993833, 2016). "Then, we investigated the mechanisms whereby Nkx2‐5 protects against atherosclerosis through its multiple actions in macrophages, smooth muscle cells, and endothelial cells." (PMID 27993833, 2016). "Considering a variety of target genes of Nkx2‐5 involved in atherosclerosis, how much of a difference will KLF4 make?" (PMID 27993833, 2016). "Although these additional functions were just preliminarily validated in cultured cells, we have reason to believe that the effects of Nkx2‐5 on atherosclerosis are comprehensive, involving multiple kinds of cells and different pathological processes." (PMID 27993833, 2016). "As well, Nkx2‐5 significantly represses expression of adhesion molecules in endothelial cells and therefore improves endothelium functions and inhibits progression of atherosclerosis at an early stage." (PMID 27993833, 2016). "Given that the majority of MMPs could be regulated by Nkx2‐5, it was hard to determine which dominated in the progression of atherosclerosis and a comprehensive effect should be taken into consideration." (PMID 27993833, 2016). "In the present study, intraventricular adenovirus gene transfer was used to manipulate Nkx2‐5 expression in aorta, and exposure of mice to a Western diet before adenovirus administration reflected the situation of elderly patients with pre‐existing atherosclerosis." (PMID 27993833, 2016). "However, the role of Nkx2‐5 in atherosclerosis remains elusive." (PMID 27993833, 2016). "Besides involving in extracellular matrix remodeling and leukocyte‐endothelium interaction, Nkx2‐5 could exert more actions predicted to influence the progression of atherosclerosis, such as inflammatory response, phenotypic switching, and arterial vasomotoricity." (PMID 27993833, 2016). "We could not ignore that Nkx2‐5 also augmented expression of interferon‐gamma, which could exacerbate atherosclerosis as an important activator of macrophages and inducer of adaptive immunity." (PMID 27993833, 2016). "Although inhibition of NKX2-5 in healthy vessels could potentially block vital repair pathways, when NKX2-5 reactivation has already become pathological, such as in pulmonary hypertension and atherosclerosis or following angioplasty and stenting, it may be very beneficial." (PMID 38652537, 2024).
colorectal cancer (3 papers, 2008 to 2025). A primary or metastatic malignant neoplasm that affects the colon or rectum. "GALR2 hypermethylation showed a sensitivity of 85%, specificity of 95% and accuracy of 98% and the combination of GALR2 or NKX2-5 hypermethylation showed a sensitivity of 90%, specificity of 95% and accuracy of 96% for detecting colorectal cancer." (PMID 18446232, 2008).
embryonal carcinoma (3 papers, 2015 to 2021). A non-seminomatous malignant germ cell tumor characterized by the presence of large germ cells with abundant cytoplasm resembling epithelial cells, geographic necrosis, high mitotic activity, and pseudoglandular and pseudopapillary structures formation. "HIF-1 and Nkx2–5 are able to transcriptionally activate Cripto during cardiac differentiation, HIF-1 also activates CRIPTO expression in human embryonal carcinoma cells, following hypoxic conditions." (PMID 25629528, 2015).
hepatocellular carcinoma (3 papers, 2022 to 2023). A malignant tumor that arises from hepatocytes. "It has been predicted via bioinformatic analysis and confirmed by chromatin immunoprecipitation analysis that in hepatocellular carcinoma cells the promoter of ERBB2 binds to the transcription factor NKX2-5, resulting in a negative regulatory effect." (PMID 36612126, 2022).
pulmonary hypertension (3 papers, 2018 to 2024). Increased pressure within the pulmonary circulation due to lung or heart disorder. "This proposal is supported by our recent finding that NKX2-5 promoter polymorphisms are genetically associated with pulmonary hypertension in scleroderma patients." (PMID 38652537, 2024). "NKX2-5 is genetically associated with scleroderma, pulmonary hypertension, and fibrosis." (PMID 29342503, 2018). "Previous research has demonstrated the association between NKX2-5 mutations/knockdown with ASD, atrioventricular conduction blocks, pulmonary hypertension, and hyperplastic atria, supporting its status as a downstream target of STX18-AS1." (PMID 39172906, 2024). "NKX2-5 is upregulated in scleroderma patients with pulmonary arterial hypertension." (PMID 38652537, 2024). "The authors also show that pulmonary hypertension and vascular fibrosis are attenuated by inhibition of NEDD9, further confirming our findings that NKX2-5 is a critical regulator of vascular remodeling." (PMID 38652537, 2024). "We also report that NKX2-5 can be detected in adult remodeled blood vessels from PAH patients, but not in healthy blood vessels, while conditional NKX2-5 deletion inhibits adaptive vascular remodeling in a mouse model of pulmonary hypertension." (PMID 38652537, 2024).
scleroderma (3 papers, 2018 to 2025). Scleroderma is a rare autoimmune connective tissue disorder characterized by abnormal hardening of the skin and, sometimes, other organs. "We explored NKX2‐5 expression in biopsy samples from patients with SSc‐associated PH and in pulmonary artery smooth muscle cells (PASMCs) from patients with scleroderma." (PMID 29342503, 2018). "In addition, NKX2-5 promoter polymorphisms were genetically associated with PH in scleroderma patients, and NKX2-5 was identified as a key regulator of SMC phenotypic modulation during pathological vascular remodeling." (PMID 40563413, 2025).
Bradycardia (2 papers, 2018 to 2025). A slower than normal heart rate (in adults, slower than 60 beats per minute). "In the present study, a novel Tyr274Ser mutation in the NKX2-5 gene was identified in a patient with bradycardia caused by an AV block." (PMID 40255339, 2025). "The atrial-specific knockout of Nkx2-5 produced atrial hyperplasia, atrial septal defects and bradycardia." (PMID 29979676, 2018).
colon cancer (2 papers, 2008 to 2023). "Some other significant roles of Nkx2–5 in other tumors include its interactions with Mef2c in ALL, with Notch3 in T cell leukemias, dysregulated Nkx2–5 expression in sarcomas and hypermethylation of Nkx2–5 in breast, prostate and colon cancer." (PMID 38110859, 2023). "In a panel of 20 colon cancer cases, all these genes except IRX5, TFAP2E and TFAP2C showed significantly higher methylation in cancer by t-test analysis (P<0.001 for NKX2-5, DPYS SPOCK2, GALR2 and SLC16A12; P = 0.008 for FOXN4)." (PMID 18446232, 2008). "Similarly NKX2-5, SPOCK2, SLC16A12, DPYS and GALR2 are candidate biomarkers for colon cancer (methylation range 60%–95%) and GALR2 hypermethylation showed a sensitivity of 85% and specificity of 95%." (PMID 18446232, 2008).
conduction disorders (2 papers, 2020 to 2021). "As Nkx2-5 mutations are highly frequent and represent 4% of CHD, deciphering cues that may drive the fate of these cells into the conductive lineage would represent a valuable strategy to treat conductive disorders and ventricular arrhythmias." (PMID 33082351, 2020).
conotruncal heart malformations (2 papers, 2017 to 2024). "The Conotruncal Heart Malformations CHTM (MIM: 217095) disorder includes the TOF malformations and is known to be causally related to gene NKX2-5, a gene also known to be causally related to TOF." (PMID 38200084, 2024).
Holt-Oram syndrome (2 papers, 2024 to 2025). Holt-Oram syndrome (HOS) is the most common form of heart-hand syndrome and is characterized by skeletal abnormalities of the upper limbs and mild-to-severe congenital cardiac defects. "In Holt–Oram syndrome, characterized by a mutation in the NKX2-5 gene, an interatrial septum defect is found in nearly 2/3 of cases, reinforcing the role of this gene in the pathogenesis of these defects." (PMID 40843896, 2025). "Holt-Oram syndrome is partially caused by variants in the TBX5 gene, and GWAS studies on AF have shown several significant loci with nearest genes known to be important for heart development and causal for CHD, such as NKX2-5, GATA4, GJA1, and GJA5." (PMID 38454350, 2024).
Hypertension (2 papers, 2017 to 2024). The presence of chronic increased pressure in the systemic arterial system. "NKX2-5 is a key determinant of phenotypic modulation in smooth muscle cells, and NKX2-5 deficiency ameliorates experimental hypertension and vascular remodeling in a hypoxia-driven mouse model." (PMID 38652537, 2024). "In vivo, conditional deletion of NKX2-5 attenuated blood vessel remodeling and halted the progression to hypertension in a mouse chronic hypoxia model." (PMID 38652537, 2024).
preeclampsia (2 papers, 2016 to 2022). Preeclampsia is a hypertensive disorder of pregnancy that is characterized by new-onset hypertension with proteinuria presenting after 20 weeks of gestation, and depending on mild or severe forms may initially present with severe headache, visual disturbances, and hyperreflexia. "In humans, placental NKX2-5 expression is significantly elevated in cases of severe preeclampsia, a complication of pregnancy that is mediated by the placenta." (PMID 35462239, 2022).
Stroke (2 papers, 2023 to 2025). Sudden impairment of blood flow to a part of the brain due to occlusion or rupture of an artery to the brain. "In further stroke subtype analyses, the authors identified risks loci EDNRA and LINC01492 for large artery disease and RGS7 and NKX2-5 for cardioembolic stroke." (PMID 38132662, 2023).
systemic sclerosis (2 papers, 2018 to 2024). A chronic disorder, possibly autoimmune, marked by excessive production of collagen which results in hardening and thickening of body tissues. "We sought further confirmation of our hypothesis that vascular injury and TGF-β superfamily signaling combine to reactivate NKX2-5, using the TGFβR2 kinase–deficient model, which recapitulates key pathological features of systemic sclerosis." (PMID 38652537, 2024).
T-cell leukemia (2 papers, 2023 to 2025). A malignant disease of the T-lymphocytes in the bone marrow, thymus, and/or blood. "Furthermore, we performed an enhancer-inhibition assay as we described for analysis of the transcriptional regulation of NKL homeobox gene NKX2-5 in T-cell leukemia." (PMID 41153416, 2025).
thyroid cancer (2 papers, 2018 to 2019). "Besides, NKX2-5 translocates to nuclear and is modified by DNA methylation that could cause poor differentiation of thyroid cancer cells." (PMID 31126066, 2019). "By the way, the overexpression of NKX2-5 could increase the production of hydrogen peroxide and promote the carcinogenic progression of thyroid cancer." (PMID 31126066, 2019). "Further, MIR130A could inhibit NKX2-5 to reduce cancer cell proliferation, migration and dedifferentiation, but it is significantly downregulated in thyroid cancer cells." (PMID 31126066, 2019).
Atrioventricular septal defects (1 paper, 2016). "Atrioventricular septal defects (AVSD) are a rare cardiac malformation associated to date with a handful of canonical genes in cardiac development (NKX2-5, GATA4, GATA6, CRELD1) and may co-occur with certain rare syndromes." (PMID 27058611, 2016).
Bicuspid aortic valve (1 paper, 2019). The presence of an aortic valve with two instead of the normal three cusps (flaps). "Analyses completed by sex discovered dissimilar variants related to bicuspid aortic valve (BAV) in men (EGFR rs533525993 and TEX26 rs12857479) and females (NKX2‐5 rs2277923)." (PMID 30834692, 2019).
cannabis dependence (1 paper, 2022). Physical and psychological dependence on the drug cannabis. "Myogenesis was identified in this screen, including myogenesis of germ cell tumor lines (2 genes, NKX2-5 and WNT3A, page 320, p = 0.00177, cannabis dependence) and myogenesis of carcinoma cell lines (2 genes, NKX2-5 and WNT3A, page 320, p = 0.00177)." (PMID 35897396, 2022).
cardiac septal defect (1 paper, 2019). "This study designed to study the association of five single–nucleotide variants of NKX2‐5, GATA4, and TBX5 genes with sporadic nonsyndromic cases of a congenital cardiac septal defect in Egyptian children." (PMID 30834692, 2019).
cerebral atherosclerosis (1 paper, 2023). Atherosclerosis of the cerebral vasculature. "The cerebral atherosclerosis-related gene PITX2, RGS7, NKX2-5, NKX2-5, and ZFHX3 are involved in AIS." (PMID 37265472, 2023).
cervix carcinoma (1 paper, 2016). "In particular, the cervix carcinoma produced high levels of NKX2-1, NKX2-2 and NKX2-5." (PMID 27876760, 2016).
esophageal squamous cell carcinoma (1 paper, 2025). Esophageal squamous cell carcinoma (ESCC) is a type of esophageal carcinoma (EC) that can affect any part of the esophagus, but is usually located in the upper or middle third. "This study reveals that hypermethylation of under‐methylated regions (UMRs) within gene bodies is involved in the activation of oncogenic homeobox genes, particularly NKX2‐5 and LHX1, in esophageal squamous cell carcinoma (ESCC)." (PMID 40307990, 2025).
hypogonadism (1 paper, 2022). A disorder characterized by decreased function of the gonads. "In particular, the NKX2-5 p.Arg25Cys missense variant has been repeatedly reported in patients with congenital heart defects and, more rarely, with hypogonadism." (PMID 36468928, 2022).
Immunodeficiency (1 paper, 2019). Failure of the immune system to protect the body adequately from infection, due to the absence or insufficiency of some component process or substance. "Besides, the expression of JAM3 is decreased in this progression and its defection may cause immunodeficiency in mice, which in turn reduces tumor immune surveillance; in the second pathway, homeobox protein NKX2-5 upregulates target genes PAP2C and JMY, which can lead to cancer cell apoptosis." (PMID 31126066, 2019).
metastatic cancer (1 paper, 2008). A carcinoma which has spread from the original site of growth to another anatomic site. "NKX3A, a homolog of NKX2–5 that functions to activate N-cadherin expression in cardiac development, may function in a similar manner by activating N-cadherin expression, which has been shown to be highly expressed in metastatic cancer cells and is upregulated during RPE de-differentiation." (PMID 18682805, 2008).